ANO1 (anoctamin 1)
Diseases named in the same sentence as ANO1 in open-access papers (continued):
Sharing a sentence is not in itself a finding about the gene and the disease.
cancer (continued). "Based on the overexpression of ANO1 in diverse cancers, ANO1 may be an important ion channel for cancer development and metastasis." (PMID 32357567, 2020). "A number of physiological and pathological processes such as ischemia and cancer progression involve alterations in extracellular pH, hence pH sensing of ANO1 could be of high relevance." (PMID 33250781, 2020). "The anti-cancer activity of Aa3 was also confirmed in ANO1 overexpressing NCI-H460 cells." (PMID 33172169, 2020). "ANO1 amplification and overexpression have been reported in various carcinomas." (PMID 32899792, 2020). "Taken together, the multiple anti-cancer effects described for the ANO1-inhibitor niclosamide, may correspond to the wide range of pro-cancerous mechanisms by ANO1." (PMID 30893776, 2019). "Meanwhile, ANO1 has been found in a number of different malignant tumors." (PMID 30893776, 2019). "Nevertheless, other ANO1-inhibitors also blocked cell proliferation and cancer growth." (PMID 30893776, 2019). "Blocking ANO1 appears feasible to interfere with cancer growth." (PMID 30893776, 2019). "Poor prognosis of ANO1-expressing cancers might be explained by the fact that EMT is closely associated with drug resistance and/or stemness of cancer cells." (PMID 29416639, 2018). "ANO1 expression was significantly associated with shorter survival of patients in only the HPV-negative cancers (Log-rank, P = 0.005) but not in HPV-positive cancers (Log-rank, P = 0.560)." (PMID 29416639, 2018). "However, further study is needed to clarify the roles and clinical significance of the expression of ANO1 in human malignant tumors." (PMID 29416639, 2018). "However, the effect of ANO1 on the cellular proliferation differed according to the phenotype of cancer cells." (PMID 29416639, 2018). "Recently, it has been reported that ANO1 has roles in the progression of human malignant tumors." (PMID 29416639, 2018). "Similarly, there are inconsistent reports regarding the role of ANO1 in the proliferation of cancer cells." (PMID 29416639, 2018). "The ANO1 inhibitor CaCCinh-A01 decreases cancer cell proliferation by facilitating degradation of ANO1 protein, while T16Ainh-A01, another small molecule inhibitor of ANO1, cannot inhibit the proliferation of these cell lines, although both compounds have been reported to inhibit ANO1 activity." (PMID 27732935, 2016). "Transcriptional regulation occurring in the ANO1 promoter region could provide a clue to the aberrant ANO1 expression in cancer." (PMID 26811235, 2016). "ANO1 is upregulated in numerous types of cancers and thus thought to be involved in tumorigenesis." (PMID 26811235, 2016). "Having shown that ANO1 and EGFR form a functional complex and that EGFR-signaling regulates ANO1-protein levels in cancer cells, we wondered whether ANO1 would affect EGFR protein levels in these cells." (PMID 25823819, 2015). "To test whether EGFR-signaling regulates ANO1-expression in cancer cells, we generated Te11 cells stably expressing a dox-inducible version of EGFR or lz-EGFR (Te11-EGFR, Te11-lz-EGFR)." (PMID 25823819, 2015). "Notably, Recent evidence strongly suggests ANO1 involvement in cell proliferation, cell migration, tumorigenesis and cancer progression." (PMID 26196390, 2015). "One hypothesis for the mechanism underlying ANO1′s channel-independent function in promoting EGFR-signaling and cell proliferation is that ANO1 exhibits its function in cancer cells by interacting with membrane proteins." (PMID 25823819, 2015). "Recently, attention has been focused on the role of Ano1 in cancers." (PMID 25961581, 2015). "Knockdown of ANO1 inhibits EGFR-signaling in cancer cells, by a yet undefined mechanism." (PMID 25823819, 2015).
cancer (continued). "A recent study comparing the PDAC cells and the normal human pancreatic ductal epithelial (HPDE) cells showed that anoctamin 1 (ANO1), also known as transmembrane member 16A (TMEM16A), a voltage sensitive calcium-activated chloride channel expression is specifically increased in cancer cells." (PMID 26264026, 2015). "Furthermore, Ano1 has been found to regulate different signaling pathways in different cancer cells." (PMID 25961581, 2015). "All cancer cell lines showed an upregulation of ANO1 on mRNA and protein levels." (PMID 25163766, 2015). "Downregulation of ANO1 induces apoptosis in several cancer cell lines overexpressing ANO1." (PMID 26196390, 2015). "Finally, studies on Ano1 in cancer cells suggest that the chloride conductance appears to be a novel regulator of ERK signaling." (PMID 24663380, 2014). "Taken together, these data provide strong evidence that CaCCinh-A01 inhibits proliferation of ANO1-amplified cancer cell lines by decreasing ANO1 protein levels, suggesting that both ANO1-activity and protein are necessary for its role as a survival factor in cancer." (PMID 24599954, 2014). "Taking these lines of evidence together, it is reasonable to conclude that abnormal expression and activation of ANO1 correlates with the occurrence, progression and metastasis of cancer and that ANO1 could be an important target of therapeutic drugs." (PMID 24316695, 2014). "Our results provide impetus for gaining a deeper understanding of ANO1 modulation in cells, which could impact the treatment of ANO1-amplified cancers." (PMID 24599954, 2014). "Therefore, the authors thought that ANO1 determined the direction while ANO6 the speed of cancer cell migration." (PMID 24639373, 2014). "In the following study, the Duvvuri group selected UM-SCC1 and T24 cell lines to evaluate whether the role of ANO1 in cancer cell proliferation is dependent on the 11q13 amplification." (PMID 24639373, 2014). "Clarification of the reasons in future will avail to make ANO1 as a target for cancer treatment." (PMID 24639373, 2014). "At the moment, one may ask: does the overexpressed ANO1 increase or reduce the [Cl−]i in cancer cell lines?" (PMID 24639373, 2014). "Significance: Our results may provide a new targeting approach for antitumor therapy in ANO1-amplified cancers." (PMID 24599954, 2014). "ANO1 is now considered an excellent biomarker for certain cancers." (PMID 24639373, 2014). "Therefore, dysregulation of ANO1 plays a critical role in several disease states, including pulmonary diseases, hypertension, diarrhea, and cancer (2, –, 7, 11, 13)." (PMID 24599954, 2014). "Therefore, it is likely that ANO1 accelerates the migration of cancer cells by regulating the coordinated changes in cell volume and organization of cytoskeleton." (PMID 24316695, 2014). "Protein expression of ANO1 was detected in 132 (82.5%) of 160 cancer tissues." (PMID 24316695, 2014). "Recently, ANO1 was shown to promote tumorigenesis and cancer progression via activating MAPK." (PMID 23372686, 2013). "The results suggest that Ano1 may be a driver gene within the 11q13 amplicon not only in HNSCC but also in other types of carcinoma." (PMID 22912841, 2012). "Furthermore, ANO1 is one of a cassette of genes that have been suggested to drive 11q13 amplification by providing growth or metastatic advantage to cancer cells." (PMID 20664600, 2010). "Consequently, increased ANO1 levels in cancer cells trigger both intracellular and extracellular pathways that modify cholesterol metabolism and activate fibroblasts, thus facilitating cancer metastasis." (PMID 40396170, 2025). "Furthermore, ANO1’s role in regulating cell volume, ion flux, and membrane potential may influence how cells respond to inflammatory environments, potentially aiding cancer survival and progression." (PMID 39941737, 2025). "In addition, ANO1 promotes proliferation, migration and invasion in certain cancers." (PMID 38685684, 2024).
cancer (continued). "Moreover, since ANO1 was highly expressed in various cancer types other than GI cancers, it may hopefully be a pan‐cancer immunotherapy biomarker and a target for precision treatment." (PMID 37341301, 2023). "This suggests that other ANOs besides ANO1 may play similar roles in cancer cell progression." (PMID 36497413, 2022). "However, it is not clear whether ANO1 contributes to cancer development by releasing chloride through ANO1 activation or whether ANO1 is a signal transduction of cancer development through protein expression of ANO1." (PMID 34281152, 2021). "However, ANO1 overexpression is a critical target in various carcinomas." (PMID 34281152, 2021). "Thus, ANO1 may be a potential drug target for cancer therapy, and ANO1 inhibitors may have therapeutic potential for cancer treatment." (PMID 32899792, 2020). "Since ANO1 surface expression and chloride currents were regulated by CaMKIIβ in U251 cells, we examined whether gene silencing of CaMKIIβ or ANO1 affect the characteristics of cancer cells, such as invasion and migration." (PMID 32357567, 2020). "However, ANO1 is often overexpressed in the cell membrane or cytoplasm when cancer develops." (PMID 31266974, 2019). "Therefore, further study is needed to determine if ANO1 could be a new therapeutic target in treatment of human malignant tumors." (PMID 29416639, 2018). "Therefore, further study is needed to clarify the exact role of ANO1 in human malignant tumors." (PMID 29416639, 2018). "In addition, although there are limited reports, the control of cancer metastasis could be archived by the regulation of ANO1." (PMID 29416639, 2018). "However, there are conflicting reports regarding the role of ANO1 in human malignant tumors." (PMID 29416639, 2018). "Therefore, other roles of ANO1 other than for the proliferation of cells might be responsible for the progression of ANO1-expressing cancers." (PMID 29416639, 2018). "Therefore, inhibition of ANO1 might be a therapeutic strategy for the treatment of human malignant tumors." (PMID 29416639, 2018). "Changes in Ano1 expression have been reported to determine whether cancer cells grow or migrate." (PMID 29156699, 2017). "Thus we believe that the dual effect of luteolin on protein levels and channel activities of ANO1 may be more beneficial for the downregulation of ANO1 in cancer cells." (PMID 28362855, 2017). "Moreover, silencing ANO1 arrested cancer cells at G1 phase of cell cycle." (PMID 27732935, 2016). "However, which signaling pathway is induced by the activation of ANO1 in cancer cells remains still unknown." (PMID 26811235, 2016). "However, it remains unclear how ANO1 exhibits its function on cellular signaling pathways to promote cancer growth." (PMID 25823819, 2015). "Thus, ANO1 inhibition by miconazole and plumbagin may be one of possible mechanisms of cytotoxic effects in cancer cells." (PMID 26196390, 2015). "However, the physiological function of ANO1 has been found to vary among different cancer tissues." (PMID 25163766, 2015). "Recently, it has been confirmed that ANO1/CaCC is overexpressed in several tumors, and inhibition of ANO1/CaCC channel activity may suppress the proliferation and migration of cancer cells." (PMID 26635857, 2015). "Such genes showed a lower proportion of monoallelic vs biallelic expression in cancer cell lines than some other imprinted genes, e.g., SNRPN, SGCE, NLRP2, H19, and ANO1." (PMID 40414875, 2025). "Overexpression of ANO1 and oncogenic KRAS in cancer cells were demonstrated to increase cell proliferation in vivo and vitro." (PMID 40396170, 2025). "Notable examples—such as ANO1, BAG2, DHCR7, MMP2, and TRAM2 —align with prior studies linking these genes related to cancer proliferation or metastasis in multiple cancer types." (PMID 40361356, 2025). "The expression of the ANO1 gene, which was lower in HG-ESS than LG-ESS, was different in 16 cancer species." (PMID 38167455, 2024).
cancer (continued). "Altogether, these data emphasized that ANO1‐mediated ferroptosis inhibition of cancer enhances CAF accumulation in TIME, which at least partially contributes to ANO1‐induced immunotherapeutic resistance." (PMID 37341301, 2023). "The calcium-activated chloride channel TMEM16A, previously ANO1, is upregulated in diverse cancers and commonly overexpressed in HNSCC, which is associated with poor outcomes, establishing it as a therapeutic target." (PMID 37568764, 2023). "Since ANO1 prevented cancer cells from ferroptotic death, we attributed ANO1‐facilitated on TGF‐β secretion and CAF recruitment as the consequence of increased cancer cell survival." (PMID 37341301, 2023). "To understand the expression and prognosis of ANO1 and IGF2BP2 across cancers, we used the GEPIA2 web server to analyze data containing 33 cancer subtypes derived from TCGA and GTEx databases." (PMID 35299748, 2022). "Compared with that in normal samples, ANO1 expression was significantly reduced in KIRP, PRAD, SKCM, TGCT, UCEC and UCS cancer samples, while it was significantly upregulated in ESCA, HNSC, KIRC, OV, PAAD, STAD and THYM cancer samples." (PMID 35299748, 2022). "Several ANO1-related signaling pathways, including EGFR-mediated AKT/SRC/ERK1/2 and Ras-Raf-MEK-ERK1/2, have been reported in cancer development." (PMID 34281152, 2021). "Anoctamin1 (ANO1), a novel drug target considered for the treatment of NSCLC, is a Ca2+-activated chloride channel (CaCC) overexpressed in various carcinomas." (PMID 34281152, 2021). "This compound exhibited more potent anti-cancer activity in the NCI-H460 cell line, expressing high levels of ANO1 compared with that in A549 cells that express low levels of ANO1." (PMID 33172169, 2020). "Thus, Ano1 may be used as prognostic marker for cancer patients." (PMID 29156699, 2017). "For example, both ANO1 and S100A11 have been reported to have important roles in tumorigenesis and cancer metastasis." (PMID 26902283, 2016). "TMEM16A is also known as ANO1, DOG1, TAOS2, and ORAOV2, because it was known to be amplified and overexpressed in cancers before it was identified as a CaCCs with eight putative transmembrane domains and N- and C-termini oriented towards the cytoplasm." (PMID 26657333, 2015). "Our study points out that to further target the functions of ANO1 and VRAC in cancers overexpressing these currents, development of more selective small-molecule inhibitors would be useful." (PMID 25163766, 2015). "Therefore, ANO1 may represent a promising target for cancer therapy." (PMID 24599954, 2014). "We reasoned that chloride channel activity of ANO1 takes part in cell migration which facilitates the emergence of metastasis in OSCC and in other cancers as well." (PMID 24316695, 2014). "ANO1 has been shown to interact with cytoskeletal proteins and to promote epidermal growth factor receptor/calcium/calmodulin-dependent protein kinase signaling in cancer cells, yet a detailed understanding of the involvement of ANO1 in these pathways remains unclear." (PMID 24599954, 2014). "Further experiments demonstrated that overexpression of ANO1 in T24 and UM-SCC1 cancer cells induced RAS-RAF-MEK-ERK pathway activation." (PMID 24639373, 2014). "Due to the fact that calcium signaling plays an important role in cancer progression, further investigation into the relationship between ANO1 and calcium signaling in TAZ-AXL-CTGF-mediated cancer progression is warranted." (PMID 23372686, 2013). "According to data from Pan-cancer RNA-seq, immune cells such as resting CD4+T cells and activated mast cells were higher in ANO1-high group, while activated CD4+ Tcells and dendritic cells, plasma cells were higher in ANO1-low group." (PMID 40396170, 2025). "Anoctamin 1 (ANO1), also known as transmembrane protein 16A, is a calcium-activated chloride channel that is upregulated in various cancer cells and contributes to cancer progression." (PMID 38659592, 2024).
cancer (continued). "ANO1 amplification's predictive value to adverse immunotherapeutic outcome retained for either GC (with statistical significance) or nonGC (EC+CRC+other cancers, with statistical tendency)." (PMID 37341301, 2023). "CAI/BBR were feasible to inhibit ANO1's protein expression and the in vitro proliferation of multiple human GC, EC, CRC cell lines as well as a mouse cancer cell line MC38." (PMID 37341301, 2023). "Since ANO1 is highly expressed in cancer tissue, exploiting its inhibition can induce ferroptosis selectively on cancer cells rather than on immune cells while suppressing accumulation/function of CAFs in TIME." (PMID 37341301, 2023). "A previous report suggested that membrane localization of ANO1 is important for cancer cell migration independent of chloride channel activity." (PMID 36690845, 2023). "Furthermore, inhibition of ANO1, through knockdown or drug inhibition, reduces the expression of EGFRvIII, NOTCH1, and other cancer stem cell markers." (PMID 36497413, 2022). "Linking these concepts and evidence together, it is apparent that ANOs, particularly ANO1, may bridge the link between EGFR signalling and calcium signalling to regulate cancer cell proliferation, migration, and invasion." (PMID 36497413, 2022). "Anoctamin-1 (ANO1), as one of the human chloride channel proteins, is frequently upregulated in different types of human cancers and is involved in AKT and MAPK signaling activation, which plays a critical role in cancer progression." (PMID 35800370, 2022). "Among the recently discovered ANO1 blockers, MONNA, Ani9, CaCCinh-A01, T16Ainh-A01, tannic acid, idebenone, luteolin, and Aa3 showed the highest potency and selectivity for ANO1 and inhibited cell proliferation in various cancer cell lines." (PMID 34281197, 2021). "Because the small-molecule inhibitors targeting ANO1 have been to date evaluated only in vitro, we investigated whether MCL1-mediated decrease of cancer cell viability is achievable by utilization of MCL1 inhibitor that is under clinical investigation." (PMID 33803266, 2021). "Although pharmacological inhibition of ANO1 reportedly inhibits the growth of various cancer cells, the potency, selectivity, safety, stability and mechanism of action of ANO1 inhibitors in NSCLC have not been identified." (PMID 34281152, 2021). "In addition, ANO1 is highly expressed in HCT116, SW480 and MCF-7 cancer cells, where cinobufagin showed anticancer activity in previous studies." (PMID 34769467, 2021). "As observed in the case of tongue, genes associated with overall cohort, IL1RAP, ANO1, RYK, AP2M1, MFN1 and PSMD2 were significant prognosticators only in the late stage not in early cancers." (PMID 31310629, 2019). "Ca2+ activated Cl− channels (TMEM16A; ANO1) support cell proliferation and cancer growth." (PMID 31060306, 2019). "Despite involvement of ANO1 in cell motility, inhibition of ANO1 did not influence the proliferation of cancer cells." (PMID 29416639, 2018). "Anoctamin1 (ANO1)/transmembrane protein 16A (TMEM16A), a calcium-activated chloride channel (CaCC), is involved in many physiological functions such as fluid secretion, smooth muscle contraction, nociception and cancer progression." (PMID 27219012, 2016). "Most studies about ANO1 focus on the cancer derived from epidermal tissue, in which ANO1 is non-specific." (PMID 27153560, 2016). "In agreement with this, none of the ANO1-overexpressing cancer cells showed any significant decrease in proliferation in response to T16Ainh-A01." (PMID 25163766, 2015). "It is not quite clear how overexpression or dysregulation of ANO1 contributes to cancer development." (PMID 26305547, 2015). "ANO1 inhibitors or RNAi-directed knockdown showed significant decrease in migration but not proliferation of cancer cells implying that calcium aberrancies contribute to EMT in cancer cells." (PMID 26264026, 2015).